UBA52 (ubiquitin A-52 residue ribosomal protein fusion product 1)
Diseases named in the same sentence as UBA52 in open-access papers:
UBA52 is named in the same sentence as 46 diseases in open-access papers, as found by Europe PMC text mining. Sharing a sentence is not in itself a finding about the gene and the disease. The quoted sentences say what the papers report.
hepatoma (7 papers, 2021 to 2024). "Upregulated UBA52 has been found in the contexts of diabetic nephropathy and hepatoma cell apoptosis." (PMID 38166541, 2024). "In traumatic brain injury, altered mRNA and protein levels of UBA52 have been observed, while in diabetic nephropathy and hepatoma cell apoptosis, upregulated UBA52 was found." (PMID 36497031, 2022). "UBA52 and RPS27A genes were found to be differently over-expressed during hepatoma cell apoptosis." (PMID 34445327, 2021).
colorectal cancer (6 papers, 2020 to 2026). A primary or metastatic malignant neoplasm that affects the colon or rectum. "UBA52 is essential for preimplantation embryo development and be able to promote tumorigenesis of non-small cell lung and colorectal cancer." (PMID 35090552, 2022). "Studies reported that PSMA7 expression was elevated in testicular, liver, breast, prostate, cervical, gastric, and colorectal cancers, while UBA52 is overexpressed in the colon, and renal cancers." (PMID 34777463, 2021). "In colorectal cancer, lncRNA LUCAT1 binds to UBA52, which encodes ubiquitin and 60s ribosomal protein L40(RPL40), and affects its stability in a proteasome dependent manner." (PMID 34888249, 2021). "In addition, applying HEART on two subpopulations of megakaryocytes, we found several potential cancer biomarkers (CTTN, S100A4, S100A6, UBA52, FAU, and VIM, etc.)associated with colorectal cancer progression and metastasis in literature." (PMID 36523772, 2022).
COVID-19 (6 papers, 2022 to 2025). A disease caused by infection with severe acute respiratory syndrome coronavirus 2. "It was discovered that the levels of two of the four ribosomal fusion proteins encoded by human ubiquitins, RPS27A and UBA52, were elevated in patients with Alzheimer's disease and COVID-19 with Alzheimer's disease, respectively." (PMID 37521843, 2022). "In influenza, UBE2S, USP53, and TIMM10 were observed in this category, while in COVID-19, UBE2T, UBE2C, DTL, MT-ND2, UCHL1, and UBA52 were implicated." (PMID 41020849, 2025). "In addition, UBA52 was found to be highly expressed in patients with COVID-19, which may be related to COVID-19 pathogenesis." (PMID 37007947, 2023). "In COVID-19, these included RPL13A, RPL6, RPL13, RPLP2, RPS11, UBA52, and the ribosomal pseudogene RPL13AP20." (PMID 41020849, 2025). "Our study uncovered six genes named RAD51, ALDH1A1, UBA52, CUL3, GADD45B, and CDKN1A were found to be commonly dysregulated among HFRS and COVID-19." (PMID 37234545, 2023). "The protein–protein interaction (PPI) network of DEGs was then constructed and six genes named RAD51, ALDH1A1, UBA52, CUL3, GADD45B, and CDKN1A were identified as the commonly dysregulated hub genes among HFRS and COVID-19." (PMID 37234545, 2023). "Among the enriched significant pathways, the Coronavirus disease-COVID-19-related pathways is the most significant pathway which involved most of the hHub-DEGs notably, CXCL8, EGFR, IL6, JUN, MAPK1, STAT3, TNF, and UBA52." (PMID 36016137, 2022). "Ultimately, EEF1A1, EGR1, UBA52, DDX5 and IRF8 might be the key shared pathogenesis-related genes in COVID-19 and asthma." (PMID 36575422, 2022). "Therefore, it is possible that UBA52 and CUL3 may also play a role in the pathogenesis of COVID-19 and HFRS coinfection through their involvement in the ubiquitin-proteasome system." (PMID 37234545, 2023).
colon carcinoma (4 papers, 2019 to 2025). "RPS27A and UBA52, which are hub proteins unique to papillary urothelial carcinoma in network A, have been found to be overexpressed in colon cancer, prostate cancer, and leukemia." (PMID 41342186, 2025).
diabetes (4 papers, 2014 to 2022). "Ubiquitin ribosomal fusion protein (UBA52) is detected in urine of patients with diabetes, which is identified as a diagnostic marker for diabetes and may be a potential therapeutic target." (PMID 30521536, 2018). "UBA52 is a diagnostic marker for diabetes, which may be a potential therapeutic target." (PMID 30521536, 2018). "For example, the ubiquitin fusion protein UbA52, mainly localized in kidney tubules, was found to increase in patients with diabetes." (PMID 33968925, 2021). "Moreover, studies found the ubiquitin fusion protein UbA52 increased significantly in urine of diabetes mellitus with macro- or microalbuminuria (DM-NP) patients by proteomic analysis." (PMID 24991536, 2014).
Parkinson disease (4 papers, 2022 to 2025). A progressive degenerative disorder of the central nervous system characterized by loss of dopamine producing neurons in the substantia nigra and the presence of Lewy bodies in the substantia nigra and locus coeruleus. "UBA52 plays a vital role in HSP90 ubiquitination and neurodegenerative signaling in Parkinson’s disease." (PMID 39796173, 2025). "Moreover, Parkinson’s disease (NDUFA9, TUBB4B, etc.; p-value = 4.94E-21), Prion disease (UQCR10, SDHA, etc.; p-value = 4.82E-17) and Pathways of neurodegeneration - multiple diseases (UBA52, etc.; p-value = 6.44E-16) were linked to the low abundant proteins in HF." (PMID 36891514, 2023).
diabetic nephropathy (3 papers, 2020 to 2024). "In addition, UBA52 had the highest degree of connectivity, and previous study suggested that UBA52 may be implicated in the diabetic nephropathy." (PMID 33240215, 2020).
influenza (3 papers, 2019 to 2025). An acute viral infection of the respiratory tract, occurring in isolated cases, in epidemics, or in pandemics; it is caused by serologically different strains of viruses (influenzaviruses) designated A, B, and C, has a 3-day incubation period, and usually lasts for 3 to 10 days. "The analysis revealed that the core targets of Chicoric acid against influenza are UBA52, UBC, HCK, CDKN1B, and RPS27A." (PMID 41303371, 2025). "However, UBA52 and most of the RP genes were down-regulated in this study after the influenza infection with respect to the normal cases." (PMID 31665046, 2019).
viral infection (3 papers, 2018 to 2025). "To further investigate the effect of UBA52-knockdown on immune response upon virus infection, we tested the production of some cytokines and chemokines in the supernatant of infected DF1 cells." (PMID 29867845, 2018). "UBA52 participates in H5N1 viral replication, which is linked to viral infection." (PMID 37007947, 2023).
glioma (2 papers, 2021 to 2024). A benign or malignant brain and spinal cord tumor that arises from glial cells (astrocytes, oligodendrocytes, ependymal cells). "However, the functional role and underlying mechanism of SMOC1, HIPK2, UBA52, S100A6, PPP1CB, CALD1, and TMSB4X in the occurrence and development of diffuse high-grade gliomas was still unknown." (PMID 39530009, 2024).
African trypanosomiasis (1 paper, 2022). "Topology analysis of the miRNA-gene network revealed three genes (RPS27A, UBA52 and GAPDH) involved in the regulation of critical pathways related to the development of African trypanosomiasis." (PMID 36354791, 2022).
breast carcinoma (1 paper, 2024). "UBA52 has been reported to potentially associate with the development of resistance to Lapatinib in breast cancer treatment." (PMID 38418940, 2024).
cardioembolic stroke (1 paper, 2020). "Interestingly, we did not found significant differences in UBA52 mRNA expression levels between atherotrombotic and cardioembolic stroke samples." (PMID 32175077, 2020).
Fanconi anemia (1 paper, 2020). Fanconi anemia (FA) is a hereditary DNA repair disorder characterized by progressive pancytopenia with bone marrow failure, variable congenital malformations and predisposition to develop hematological or solid tumors. "The Fanconi anemia pathway genes FANCB, POLN, DCLRE1A, UBA52, and FANCF genes were significantly (p < 0.01, T-test) downregulated after radiation only in FANCA-deficient HIO lines." (PMID 32085439, 2020).
gastric cancer (1 paper, 2025). A primary or metastatic malignant neoplasm involving the stomach. "Although there is limited evidence regarding the exact role of UBA52 in PCa, some studies have reported its upregulation in pancreatic cancer and its association with the promotion and progression of multiple myeloma and gastric cancer." (PMID 41187218, 2025).
injury (1 paper, 2024). Damage inflicted on the body as the direct or indirect result of an external force, with or without disruption of structural continuity. "In traumatic brain injury, altered mRNA and protein levels of UBA52 have been observed." (PMID 38166541, 2024).
myocardial infarction (1 paper, 2024). Gross necrosis of the myocardium, as a result of interruption of the blood supply to the area, as in coronary thrombosis. "The involvement of genes such as AGPS, MYO9B, PYGB, TOM1, UBA52, and UBB in myocardial infarction is first reported in this study." (PMID 39872885, 2024).
non-small cell lung carcinoma (1 paper, 2022). A group of at least three distinct histological types of lung cancer, including non-small cell squamous cell carcinoma, adenocarcinoma, and large cell carcinoma. "Degradation of CCNB1 mediated by APC11 through UBA52 ubiquitination promotes cell cycle progression and proliferation of non-small cell lung cancer cells." (PMID 35008908, 2022).
nonalcoholic fatty liver disease (1 paper, 2024). "Similarly, Eriodictyol exhibits the potential to ameliorate nonalcoholic fatty liver disease (NAFLD) by modulating autophagy mediated by ubiquitin A‐52 (UBA52) and upregulating the Nrf2/HO‐1 (heme oxygenase‐1) signaling pathway to attenuate oxidative stress." (PMID 39554371, 2024).
Stroke (1 paper, 2020). Sudden impairment of blood flow to a part of the brain due to occlusion or rupture of an artery to the brain. "No previous records of the association between UBA52 gene and stroke have been reported to our knowledge." (PMID 32175077, 2020).
cancer (13 papers, 2016 to 2025). A tumor composed of atypical neoplastic, often pleomorphic cells that invade other tissues. "UBA52 encodes a ubiquitin-ribosomal fusion protein involved in essential processes such as protein synthesis and degradation, both of which are upregulated in rapidly proliferating cancers." (PMID 41342186, 2025). "These included RPL6, RPL7, RPL18A, RPS2, EIF3E, EIF3J, and UBA52, reflecting the elevated protein synthesis demands of cancer cells." (PMID 41228302, 2025). "Furthermore, UBA52 and RPL37 are related to ribosome pathway, and PRKC is related to the “cancer” pathway, as indicated by the KEGG analysis." (PMID 27329587, 2016).
tumor (13 papers, 2013 to 2025). "It is reported that over-expression of UBA52 induced cellular apoptosis in tumor tissue and UBA52 was mainly enriched in low-risk group in our study." (PMID 35692054, 2022). "Ubiquitin hybrid (fusion) genes, Uba52 and Uba80, encode ubiquitin fused to ribosomal proteins and are upregulated during tumor‐cell apoptosis." (PMID 27448508, 2016). "We subcutaneously implanted CCA cells, in which either ROCK2 alone was knocked down or ROCK2 and UBA52 were knocked down, into nude mice to monitor tumour growth." (PMID 40615369, 2025). "Ubiquitin A‐52 residue ribosomal protein fusion product 1 (UBA52) has a role in the occurrence and development of tumours." (PMID 38445807, 2024). "In our study, we found that downregulating UBA52 expression prevented tumour development and metastasis in mice, which is consistent with our in vitro results." (PMID 38445807, 2024). "Mechanistically, UBA52 promoted tumour tumorigenesis and metastasis by inhibiting autophagy and decreasing the expression of EMC6." (PMID 38445807, 2024). "The UBA52 protein expression level was higher in tumour tissues in HPA database by tissue microarray analysis." (PMID 38445807, 2024). "In addition, knockdown of UBA52 induced the formation of barely visible metastatic tumours in the lungs." (PMID 38445807, 2024). "The results of WGCNA showed that the turquoise and blue modules, which are highly related to the eutopic endometrial cell group and the ectopic endometrial cell group, all contained tumor related genes, such as UBC, UBA52, RPS27A, PIK3CB, IRS1, and CEACAM1." (PMID 33868805, 2021). "Meanwhile, the emergence of RUNX1 mutation, upregulations of genes expression (RPS27A, RPS6, UBA52, RACK1) on tumor cells, and increased frequencies of T and NK cells with TIGIT, CTLA4, and LAG3 expression were observed after midostaurin treatment, predicting the disease progression of this patient." (PMID 37638009, 2023).
infection (3 papers, 2018 to 2025). The state of being infected such as from the introduction of a foreign agent such as serum, vaccine, antigenic substance or organism. "Our findings suggest that UBA52 could be a main host target protein (UBA52) encoded gene by the ASFV protein I225L (UBCv1; a ubiquitin-conjugating enzyme), which potentially modulates many viral mechanisms and cellular functions in the early phase of infection." (PMID 38847223, 2024).
neurodegenerative disease (2 papers, 2017 to 2022). A disorder of the central nervous system characterized by gradual and progressive loss of neural tissue and neurologic function. "However, the role of UBB in neurodegenerative disease is well studied, and therefore, we performed studies to check alterations in the gene expression and protein level of UBA52 during the onset of PD." (PMID 36497031, 2022). "However, it is intriguing that ubiquitin A-52 (UBA-52) and polyubiquitin B (UBB) are not on top of the list; especially as UBB is involved in several neurodegenerative diseases." (PMID 28282387, 2017).
UBA52 also shares sentences with these, for which no sentence is quoted: glioblastoma (2 papers); prostate carcinoma (2); renal carcinoma (2); acute myelogenous leukemia (1); allergic rhinitis (1); Alzheimer disease (1); asthma (1); brain injury (1); cholangiocarcinoma (1); Cirrhosis (1); glaucoma (1); leukemia (1); low grade glioma (1); multiple myeloma (1); Obesity (1); ovarian carcinoma (1); pancreatic cancer (1); prion disease (1); renal cell carcinoma (1); Sepsis (1); synucleinopathies (1); thyroid cancer (1).